KCNIP4-IT1 (KCNIP4 intronic transcript 1)
Synonyms: UM9-5; NCRNA00099; UM9(5)
Gene: Long non-coding RNA gene on chromosome 4 (21,843,341 to 21,853,188, reverse strand). Ensembl gene ENSG00000280650.
Diseases named in the same sentence as KCNIP4-IT1 in open-access papers:
KCNIP4-IT1 is named in the same sentence as 1 disease in open-access papers, as found by Europe PMC text mining. Sharing a sentence is not in itself a finding about the gene and the disease.
KCNIP4-IT1 shares sentences with these, for which no sentence is quoted: tumor (1 paper).